CRP (C-reactive protein)
Diseases named in the same sentence as CRP in open-access papers (continued):
Sharing a sentence is not in itself a finding about the gene and the disease.
autoimmune hemolytic anemia (5 papers, 2011 to 2024). Autoimmune hemolytic anemia (AIHA) is an autoimmune disorder in which various types of auto-antibodies are directed against red blood cells causing their survival to be shortened and resulting in hemolytic anemia. "Serum CRP concentrations in canine autoimmune hemolytic anemia and primary IMHA are increased." (PMID 34566333, 2021). "Serum concentrations of APPs, Hp, Cp, SAA, and CRP were determined in healthy dog and dogs with different diseases, grouped as acute inflammation, hematological neoplasias [hemotologic tumor (HT)], including epithelial, mesenchymal, and mixed and autoimmune hemolytic anemia." (PMID 21430962, 2011).
Bladder Pain Syndrome (5 papers, 2013 to 2023). "Our previous studies have shown serum CRP levels were significantly higher in subjects with OAB or interstitial cystitis/bladder pain syndrome than in controls." (PMID 24454896, 2014). "Furthermore, a relatively normal CRP elevation has also been reported in overactive bladder cases and in those with interstitial cystitis/bladder pain syndrome." (PMID 37873776, 2023).
bladder tumors (5 papers, 2021 to 2025). "In one multi-institutional prospective study, 1117 patients underwent CRP measurement prior to transurethral resection of bladder tumor (TURBT)." (PMID 34512646, 2021). "Additionally, studies have shown that bladder tumors are correlated with inflammatory markers in the blood, such as CRP, CD3+, and CD8+ cells, all of which are significantly associated with survival outcomes." (PMID 40134599, 2025).
brain tumors (5 papers, 2021 to 2024). "These variables include systemic corticosteroid use and inflammatory markers such as interleukin-6 (IL-6), c-reactive protein (CRP), and erythrocyte sedimentation rate (ESR), which all have associations between elevated levels and poor prognosis in brain tumor patients." (PMID 39840266, 2024). "This is the first study to follow serial lymphocyte subsets, serum immunoglobulins (IgG, IgA and IgM), CRP, and complements (C3 and C4) levels in patients with brain tumors treated with neurosurgical tumor resection and to correlate the findings with postoperative infection complication." (PMID 36169250, 2022). "Considering the accessibility, convenience and cost–benefit analysis among the assessing methods, lymphocyte subsets, serum immunoglobulins, CRP, and complements levels are routinely measured in patients with brain tumors during perioperative period in our institute." (PMID 36169250, 2022). "However, many other studies showed that CRP does not associate with prognosis in brain tumor patients." (PMID 33584142, 2021).
bronchiolitis obliterans syndrome (5 papers, 2009 to 2025). A lung disorder that is mainly associated with chronic allograft dysfunction after lung transplantation and that is characterized by inflammation and fibrosis of bronchiolar walls that reduce the diameter of the bronchioles and result in progressive and irreversible airflow obstruction. "The local immunoreactivity of C-reactive protein (CRP) was studied in a heterotopic porcine model of posttranplant obliterative bronchiolitis (OB)." (PMID 19503785, 2009).
Chagas disease (5 papers, 2013 to 2023). A parasitic infection caused by Trypanosoma cruzi. "In a study conducted on children under 13 years of age in the acute phase of Chagas disease in an endemic area of Bolivia, a significant increase in alpha-2-macroglobulin and C-reactive protein concentrations was observed; this mobilization probably directly affected the albumin levels." (PMID 35371021, 2022).
chondrosarcoma (5 papers, 2018 to 2024). A malignant cartilaginous matrix-producing mesenchymal neoplasm arising from the bone and soft tissue. "We can easily confirm that risk factors for reduced prognosis lie in chondrosarcoma high grading, preoperative pathological CRP- level, and a size > 8 cm." (PMID 39001318, 2024). "For this purpose, we set up a cohort study to analyze the association of pre‐operative serum CRP with overall survival in patients with dedifferentiated chondrosarcoma." (PMID 29701260, 2018). "In light of our findings, we affirm the role of pretreatment CRP values in predicting prognosis, local recurrence, and distant metastasis in chondrosarcoma patients." (PMID 39001318, 2024). "Our research aims to assess the predictive significance of pretreatment serum CRP analysis concerning prognosis in chondrosarcoma patients." (PMID 39001318, 2024). "It is evident that assessing preoperative CRP levels in patients with chondrosarcoma holds significant prognostic value." (PMID 39001318, 2024). "It was observed that patients in our cohort who ultimately died from chondrosarcoma had, on average, higher preoperative CRP values." (PMID 39001318, 2024). "This retrospective study aimed to examine the role of C-reactive protein (CRP) as a prognostic factor in relation to the histopathological findings in chondrosarcoma." (PMID 39001318, 2024). "Our data gave evidence that baseline CRP is an independent predictor for OS in patients with dedifferentiated chondrosarcoma." (PMID 29701260, 2018). "In conclusion, our data gave evidence that baseline CRP is an independent predictor for OS in patients with dedifferentiated chondrosarcoma." (PMID 29701260, 2018). "Patients with G1 chondrosarcoma had a median CRP level of 1.5 mg/dL (0.1–6 mg/dL)." (PMID 39001318, 2024). "The prognostic significance of C-reactive protein, however, remains in chondrosarcomas unexplored." (PMID 39001318, 2024). "We can carefully speculate that the pre‐operative CRP is an independent predictor for survival in dedifferentiated chondrosarcoma." (PMID 29701260, 2018). "In evaluating the tumor size in the group with an elevated CRP, the majority had a tumor size > 8 cm (pT2, according to the 5th Edition 2020 WHO) while the group with low CRP levels was mostly represented by chondrosarcomas with <8 cm size (pT1)." (PMID 39001318, 2024).
complicated appendicitis (5 papers, 2016 to 2024). Appendicitis characterised by the presence of complications such as localised abscess, peritonitis and perforation. "CRP remains the key marker for diagnosing complicated appendicitis (CAA); however, its moderate diagnostic accuracy in detecting CAA suggests the need for new complementary biomarkers." (PMID 39451658, 2024). "In our results, complicated appendicitis was predicted by CRP at a much higher specificity of 90.3%." (PMID 35495380, 2022). "The predictive value of DNI for acute complicated appendicitis was fair (AUC 0.727) and lower than that of CRP (AUC 0.842)." (PMID 28747992, 2017). "AUCs for the ability of serum DNI and CRP to predict the presence of acute complicated appendicitis were 0.738 and 0.840, respectively." (PMID 26859663, 2016). "Eight parameters were independent risk factors for a prolonged LOS: higher age, higher preoperative WBC-count and CRP, lower preoperative hemoglobin, need for conversion, longer surgery duration, presence of intraoperative complicated appendicitis and of postoperative morbidity." (PMID 36708422, 2023). "DNI, MPXI, C-reactive protein (CRP), and white blood cells (WBCs) were measured in an emergency department and investigated with respect to their abilities to predict the presence of acute complicated appendicitis." (PMID 26859663, 2016).
developmental delay (5 papers, 2016 to 2024). "We conducted a population-based nested case–control study with 500 children with ASD, 235 with developmental delay (DD) and 580 general population (GP) controls to further investigate whether elevated CRP during pregnancy increases the risk of ASD." (PMID 27093065, 2016).
diastolic heart failure (5 papers, 2018 to 2023). Heart failure caused by abnormal myocardial relaxation during diastole leading to defective cardiac filling. "PubMed and Embase were searched for studies that assess the relationship between CRP and HFpEF using the following search terms: (((C-reactive protein) AND ((preserved ejection fraction) OR (diastolic heart failure)))." (PMID 32030562, 2021). "Patients in the Phosphodiesterase-5 Inhibition to Improve Clinical Status and Exercise Capacity in Diastolic Heart failure (RELAX) trial had baseline high-sensitivity CRP levels measured (n = 214)." (PMID 30114262, 2018). "In a follow up study, the Diastolic Heart Failure Anakinra Response Trial-2 (DHART-2), patients with stable symptomatic HFpEF were treated with Anakinra to confirm the effects on peak VO2 and CRP and observe its effects on serum NT-proBNP." (PMID 30619885, 2018).
Dysphagia (5 papers, 2022 to 2025). "Our study found that the CRP to ALB ratio is positively correlated with mortality in dysphagia patients, which can serve as a practical tool for evaluating patient outcomes in clinical practice." (PMID 38993239, 2024). "The C-reactive protein/albumin ratio was positively related to mortality in Japan older people with dysphagia patients." (PMID 38993239, 2024). "However, few studies have investigated the association between CRP/ALB and mortality in Japan older people with dysphagia patients." (PMID 38993239, 2024).
epididymitis (5 papers, 2017 to 2025). Inflammation of the epididymis. "Number of patients with active CNS and GI signs and epididymitis was insufficient to evaluate their association with ESR and CRP." (PMID 35144674, 2022). "CRP has also been assessed on penile vascular disease where there can be a slight increase (mean approx. 2 mg/L), it was also reported that epididymitis/orchitis have a greater CRP of more than 24 mg/L, whereas males with acute scrotum can show notably elevated CRP (mean 68 mg/L)." (PMID 37873776, 2023). "Furthermore, several studies have shown higher serum CRP titers in orchitis and epididymitis, in which it may aid in differentiation from other medical conditions." (PMID 37873776, 2023). "As mentioned in previous studies, our results also failed to establish a significant difference in ESR and CRP values in active CNS involvement, gastrointestinal manifestations, and patients with epididymitis." (PMID 35144674, 2022). "Second, data from diagnostic laboratory tests that can help confirm diagnoses of epididymitis and orchitis, such as urinalysis, urine culture, and C-reactive protein (CRP) level data, are not included in the NHIRD." (PMID 28316630, 2017).
esophageal adenocarcinoma (5 papers, 2015 to 2025). A malignant tumor with glandular differentiation arising predominantly from Barrett mucosa in the lower third of the esophagus. "Independent of trauma cases, visceral obesity was associated with higher CRP levels following surgery for oesophagus adenocarcinoma." (PMID 34833119, 2021). "Previous studies have found that higher circulating levels of certain metabolic and inflammatory biomarkers, including leptin, glucose, insulin, C-reactive protein, interleukin 6, and soluble tumor necrosis factor receptor 2, are associated with an increased risk of esophageal adenocarcinoma." (PMID 40917762, 2025).
fibroids (5 papers, 2022 to 2026). "In this prospective study, we reported null associations between lipids, CRP, anthropometry (except waist-to-hip ratio), and incidence of fibroids." (PMID 38625699, 2024). "According to our findings, it was found that the volume of fibroids significantly affects the CRP value on the second post interventional day, whilst also impacting the size reduction rate of fibroids, especially the largest ones, after embolization." (PMID 37763151, 2023). "Yet, a study found that CRP combined with other markers could be beneficial to distinguish leiomyosarcoma from especially degenerated or atypical leiomyoma." (PMID 37873776, 2023).
gastric ulcer (5 papers, 2016 to 2025). An ulcerated lesion in the mucosal surface of the stomach. "However, it may function as an efficient free radical scavenger, potentially contributing to CRP’s anti-gastric ulcer effects through neutralization of reactive oxygen species generated during alcohol intoxication." (PMID 40647169, 2025). "This study investigated the effects of probiotics combined with quadruple therapy on serum levels of tumour necrosis factor-a (TNF-a), interleukin-6 (IL-6), C-reactive protein (CRP), gastrin (GAS), and motilin (MTL) in patients with Helicobacter pylori (Hp)-positive gastric ulcer (GU)." (PMID 41281280, 2025). "This study aimed to explore the clinical efficacy of probiotics plus quadruple therapy on Serum levels of tumour necrosis factor-a (TNF-a), interleukin-6 (IL-6), C-reactive protein (CRP), gastrin (GAS) and motilin (MTL) in treating Helicobacter pylori (Hp)-positive gastric ulcer (GU)." (PMID 41281280, 2025).
glomerular disease (5 papers, 2021 to 2025). "Finally, RBC casts were associated with increased levels of C-reactive protein (CRP), leukocyturia, and hematuria, implicating that RBC casts represent active glomerular disease and subsequent glomerular hemorrhage." (PMID 34207078, 2021). "Furthermore, we have shown that RBC casts were associated with increased levels of C-reactive protein (CRP), leukocyturia, and hematuria, confirming the concept that RBC casts represent active glomerular disease and subsequent glomerular hemorrhage." (PMID 34207078, 2021).
glomerulosclerosis (5 papers, 2021 to 2024). A hardening of the kidney glomerulus caused by scarring of the blood vessels. "Factors associated with ESRD were serum creatinine level >500 μmol/l (P=0,0016), CRP level >60 mg/l (P = 0,0013), interstitial fibrosis (P=0,0009) and glomerulosclerosis> 10% of total glomeruli (P=0,001)." (PMID 36034042, 2022). "Activation of inflammatory mediators, such as C-reactive protein (CRP), monocyte chemotactic protein-1 (MCP-1), and inflammatory vesicles, drives macrophage infiltration, tubular fibrosis, and accelerates glomerulosclerosis." (PMID 39104818, 2024). "The activation of various inflammatory factors, such as C-reactive protein (CRP), monocyte chemoattractant protein-1 (MCP-1) and inflammasomes, promote macrophage infiltration, renal tubular fibrosis, and eventually accelerate glomerulosclerosis." (PMID 34305953, 2021).
Graves disease (5 papers, 2013 to 2023). Graves' disease is an autoimmune disorder that leads to overactivity of the thyroid gland (hyperthyroidism).It is caused by an abnormal immune system response that causes the thyroid gland to produce too much thyroid hormones. "In the present study, only the VCAM-1 level, but not the CRP level, was significantly increased in patients with Graves’ disease." (PMID 33051540, 2020).
hantavirus infection (5 papers, 2015 to 2022). "The pathophysiology of organ damage that occurs with hantavirus infection also motivates the increase in biomarkers, including ferritin, CRP, and PCT." (PMID 35677912, 2022). "In contrast, the level of CRP was normally or slightly elevated in hantavirus infection, but it was significantly increased in patients with HFRS with bacterial co-infection, which was related to the severity of infection and prognosis." (PMID 35677912, 2022). "Baseline characteristics of study population during acute hantavirus infection; CRP C-reactive protein; LDH Lactate dehydrogenase; # Clinical signs and symptoms and laboratory values were taken at time of admission to hospital." (PMID 26650941, 2015). "High serum CRP and low serum TGF-β in the early phase of hantavirus infection is associated with a severe course of disease." (PMID 25888018, 2015). "All patients showed characteristic alterations in laboratory parameters of acute hantavirus infection: elevation of leukocyte count, serum creatinine, C-reactive protein (CRP) level and lactate dehydrogenase (LDH) activity, as well as a decrease in platelet counts." (PMID 35458553, 2022). "High CRP is a marker of disease severity in hantavirus infection." (PMID 25888018, 2015).
Hematuria (5 papers, 2018 to 2024). The presence of blood in the urine. "Red blood cell (RBC) casts were associated with increased levels of C-reactive protein (CRP), leukocyturia, and hematuria." (PMID 34207078, 2021).
Henoch-Schönlein purpura (5 papers, 2018 to 2025). "β2-MG was positively correlated with CRP, which might be involved in the development of Henoch-Schönlein purpura." (PMID 31427482, 2019).
HIV-1 infection (5 papers, 2018 to 2024). The type species of lentivirus and the etiologic agent of acquired immunodeficiency syndrome (AIDS). "Other inflammatory markers reported during HIV-1 infection are IL-6 and the acute-phase reactant CRP; both have been previously correlated with mortality in HIV-1 individuals." (PMID 29963050, 2018). "Interestingly, chronic HIV-1 infection, even in the setting of long-term suppressive antiretroviral therapy, leads to increases in similar inflammation markers such as IL-6 and C-reactive protein." (PMID 36454631, 2023). "Data from other studies found that interleukin-6 [IL-6], C-reactive protein [hsCRP], soluble CD14 [sCD14], and D-dimer correlated with the overall mortality due to HIV-1 infection." (PMID 39205179, 2024). "Here we assessed plasma levels of soluble CD14 (sCD14), C-reactive protein (CRP), IL-6, and intestinal fatty acid binding protein (IFABP) at the pre-infection time point and over the course of the first 45 days of acute HIV-1 infection." (PMID 31937782, 2020).
hypertensive heart disease (5 papers, 2022 to 2025). Abnormal enlargement of the heart resulting from long-standing hypertension. "CRP, functioning as a biomarker, has been shown to increase the risk of hypertensive heart disease by 21%." (PMID 40797480, 2025). "We show, for the first time, a direct causality between higher levels of CRP and a higher risk of hypertensive heart disease (HHD)." (PMID 37298077, 2023). "In summary, we demonstrate for the first time that a genetically determined increase in CRP levels increases the risk of hypertensive heart disease by 21% (OR = 1.21 [1.07–1.37])." (PMID 37298077, 2023). "Circulating biomarkers for hypertensive heart disease, including brain natriuretic peptide (BNP), pro-BNP, soluble ST2 (sST2), C-reactive protein (CRP), cardiotrophin-1, and the ratio of neutrophil-to-lymphocyte have been extensively investigated." (PMID 35157609, 2022).
invasive breast carcinoma (5 papers, 2008 to 2023). A carcinoma that infiltrates the breast parenchyma. "Among cancer patients, those with high CRP levels had 80% risk of premature death, whereas those with elevated CRP levels with invasive breast cancer had a 1.7-fold risk of tumor-related death." (PMID 33193896, 2020). "Among the 11 hematological and biochemical biomarkers found to be associated with the risk of invasive breast cancer, some were inflammatory markers, such as white blood cell count, neutrophil count, and CRP, while others were endogenous hormones, such as SHBG, IGF-1, and testosterone." (PMID 38000092, 2023). "Using a Mendelian randomization (MR) approach, we investigated the potential causal relationship between genetically elevated C-reactive protein (CRP) concentrations and primary invasive breast cancer risk in postmenopausal women." (PMID 33614510, 2020).
mononucleosis (5 papers, 2024 to 2026). "Laboratory blood testing was mainly used for targeted mononucleosis diagnosis, but some participants used it for more general purposes, such as C reactive protein testing or long-lasting infections diagnosis." (PMID 38729758, 2024).